GCG (glucagon)
Diseases named in the same sentence as GCG in open-access papers (continued):
Sharing a sentence is not in itself a finding about the gene and the disease.
Hypoglycemia (continued). "The physiological role of AAs in stimulating glucagon secretion is most likely to prevent hypoglycemia by increasing AA catabolism and liver gluconeogenesis after protein ingestion, counteracting the anabolic effects of insulin, since AAs also stimulate beta." (PMID 35448534, 2022). "Awareness of hypoglycemia is mediated through a complex pathway involving the sympathoadrenal network and the counter-regulatory hormones, particularly glucagon." (PMID 35819935, 2022). "The glucagon stimulation test is an alternative to the insulin-hypoglycemia test for the evaluation of anterior pituitary function in adults and children." (PMID 35723775, 2022). "During hypoglycemia, glucagon secretion is part of the mechanism needed to restore normal blood glucose levels." (PMID 36180454, 2022). "Repeated hypoglycaemia induced by insulin attenuates the endocrine counter-regulatory response to hypoglycemia, which normally involves a marked increase of plasma glucagon, norepinephrine and cortisol." (PMID 35207609, 2022). "Abundant neurons in the VMH express glucokinase (GcK), and activation of these neurons increases blood glucose in mice; deletion of GcK reduces hypoglycemia-induced glucagon secretion." (PMID 35619170, 2022). "Persistent hypoglycemia was detected in three patients, and blood sugar regulation was achieved in two of them with glucagon therapy." (PMID 36382321, 2022). "In vivo glycemic regulation ability of the GRS glucagon MN patch to lower hypoglycemia risks was further assessed with a streptozotocin (STZ) ‐induced insulin‐deficient diabetic mouse model." (PMID 35957510, 2022). "Two of the earliest closed-loop systems – those developed by Kadish and Shichiri – utilized a dual-hormone approach with a combination of insulin to counter hyperglycemia and glucagon to counter hypoglycemia." (PMID 35733769, 2022). "In people with T1D, the plasma glucagon response to exercise is abolished following prolonged bouts of antecedent hypoglycaemia." (PMID 36147573, 2022). "Administrating quick-acting carbohydrates (such as glucose tablets, sugared fruit juices, or hard candy), intravenous glucose infusion, or injection of glucagon are good methods to correct hypoglycemia immediately." (PMID 36034453, 2022). "During hypoglycemia, the pancreas decreases the secretion of insulin and increases the secretion of glucagon." (PMID 36687427, 2022). "Hypoglycemia requires immediate correction, and can be managed, depending on its severity, through ingestion of glucose, glucagon injection, or intravenous glucose solution." (PMID 36550552, 2022). "Pancreatic α-cells respond to hypoglycemia with an increase in their intracellular calcium levels, which promotes glucagon secretion." (PMID 35121731, 2022). "It has been shown that GIP stimulates insulin release to exert hypoglycemic effects under hyperglycemic conditions, while stimulating glucagon secretion to reduce the occurrence of hypoglycemia in hypoglycemic states." (PMID 36119737, 2022). "We found that increased Irak4 expression, leading to increased Il-1ß signaling, reduced hypoglycemia-induced glucagon secretion." (PMID 36180454, 2022). "Glucagon is used clinically to treat severe hypoglycemia; injection or nasal administration of pharmacologic doses of glucagon rapidly increases glucose levels within 10–15 min." (PMID 34027090, 2021). "Hypoglycaemia elicits a typical response consisting of secretion of counter-regulatory hormones (glucagon, cortisol, catecholamines and growth hormone) and activation of the autonomic nervous system (ANS), which collectively act to raise glucose levels." (PMID 33241460, 2021). "Since we did not observe changes in glycaemia, we examined the counter-regulatory response to hypoglycemia which is mediated, in part, by glucagon from the pancreatic islets." (PMID 34209137, 2021).
Hypoglycemia (continued). "Intramuscular glucagon as bolus provided a glycemic rise with a secondary rebound of hypoglycemia, whereas continuous intravenous glucagon infusion was ineffective." (PMID 34635134, 2021). "In keeping with a GSD 0‐like condition, an emergency high dose of i.m. glucagon (2 × 2 mg) during a KH attack only led to a maximum glucose concentration of 70 mg/dL (3.9 mmol/L), followed by rebound hypoglycemia." (PMID 34765400, 2021). "Although there is little conservation between AKH and glucagon amino acid sequences, both hormones act through the same evolutionarily conserved signaling pathway to regulate transcriptional responses to hypoglycemia." (PMID 35002748, 2021). "It is anticipated that the availability of fast-acting glucagon will expand the use of glucagon, improve overall metabolic control, and prevent hypoglycemia-related complications, in particular cardiovascular complications and cognitive impairment." (PMID 34638984, 2021). "GLP1 also enhances β-cell number and mass through β-cell proliferation and neogenesis and decreases glucagon secretion in a glucose-dependent fashion that prevents hypoglycemia." (PMID 33440821, 2021). "However, diabetic patients with repeated hypoglycemic episodes may display a progressive deficiency in their ability to respond to hypoglycemia by inappropriate secretion of glucagon and other counterregulatory hormones such as epinephrine, cortisol, and growth hormones." (PMID 34354571, 2021). "When various types of stimulation, including hypoglycemia, were applied in a study using mice, female mice showed greater increase in blood glucagon levels than male mice." (PMID 34199839, 2021). "The sympathoadrenal counterregulatory response to hypoglycemia is critical for individuals with type 1 diabetes due to impaired ability to produce glucagon." (PMID 34444787, 2021). "The CRR is the neuro-endocrine response to hypoglycemia that involves an increase in glucagon, corticosterone, and norepinephrine levels, and a reduction in insulin secretion." (PMID 34265067, 2021). "The study's main weakness is that the simulations were preceded by a lecture that covered generic resuscitation steps, doses of adrenalin therapy in anaphylaxis and cardiac arrest, and glucose and glucagon therapy in hypoglycemia." (PMID 34515607, 2021). "An effect of SSTR2a on glucagon secretion during hypoglycemia has previously been shown in streptozotocin-induced diabetic rats and has been suggested as a target to restore the glucagon response to hypoglycemia in type 1 diabetes." (PMID 33434183, 2021). "Pancreatic islet α- and β-cells are regulated by glucose concentrations, with hypoglycemia-triggering α-cells release glucagon and hyperglycemia-stimulating β-cells secret insulin." (PMID 34354571, 2021). "Even though nasal glucagon, self-injected stable glucagon, and dasiglucagon are effective in resolving severe hypoglycemia, it would be reassuring to show that overall metabolic control improves as well in patients using these emergency drugs." (PMID 34638984, 2021). "OGT is highly expressed in pancreatic glucagon-secreting cells (α-cells), which secrete glucagon in response to hypoglycemia." (PMID 33460647, 2021). "In normal conditions, hypoglycemia stimulates glucagon secretion to increase blood glucose levels with glycogenolysis." (PMID 34067286, 2021). "Based on observations in isolated (ex vivo) islets, hypoglycemia has been postulated to stimulate glucagon secretion via intrinsic and/or paracrine mechanisms." (PMID 34787082, 2021). "This has opened the way to the use of glucagon mini-doses that have recently been administered at doses of 100–150 μg instead of 1 mg, both in adults and in infants, to prevent or to treat mild hypoglycemia." (PMID 34638984, 2021). "AVP also mediates the stimulatory effects of hypoglycemia produced by exogenous insulin and 2-deoxy-D-glucose on glucagon secretion." (PMID 34787082, 2021).
Hypoglycemia (continued). "IN glucagon was developed in 2010 and continued in 2015; in 2019 IN glucagon obtained approval in the US, Canada, and Europe for severe hypoglycemia in children and adults." (PMID 34638984, 2021). "In contrast, SSTR2 antagonism increased insulin during hyperglycemia as well as increased glucagon secretion during hypoglycemia." (PMID 33434183, 2021). "Just as importantly–because glucagon must be secreted only during hypoglycemia–increasing glucose concentrations to 6 mM rapidly closes all remaining α cell KATP channels." (PMID 35002748, 2021). "During hypoglycemia, plasma glucagon, noradrenaline and somatotropin increased in both groups, without any difference in the baseline-subtracted area under the curve." (PMID 34085953, 2021). "Management approaches:Diet and lifestyle advice.Medications: glibenclamide, metformin, glucagon, glucose injectable (hypoglycemia), insulin (soluble, intermediate, rapid human)." (PMID 33777712, 2021). "In contrast, during hypoglycemia, glucagon secretion is promoted, which increases blood glucose levels by hepatic glucose production." (PMID 33808424, 2021). "We also identified intramuscular glucagon as the most frequently used agent during on-scene management to reverse severe hypoglycaemia in Kuwait." (PMID 34051726, 2021). "Hypoglycemia increases blood glucagon, cortisol, and catecholamine levels, leading to gluconeogenesis, lipolysis, glycogenolysis, and the consumption of ketone bodies." (PMID 34438764, 2021). "Severe hypoglycemia, for instance, is an index of glucagon disequilibrium and impairment of alpha pancreatic cells." (PMID 34572493, 2021). "Several studies have explored the antidiabetic potential of PACAP due to the modulation of glucose-induced insulin secretion, the proliferation of islet cell mass, and increased glucagon response to insulin-induced hypoglycemia." (PMID 33809145, 2021). "In response to increases in glucagon levels triggered by conditions such as fasting and hypoglycemia, hepatic glucose production is promptly stimulated via the gluconeogenesis process." (PMID 34336923, 2021). "The only dry nasal glucagon spray in the market, Baqsimi (glucagon, Eli Lilly), has been approved for treating severe hypoglycemia for four-year-old patients or older." (PMID 33802091, 2021). "Due to the importance of glucagon to prevent life-threatening hypoglycemia, several mechanisms are likely to be involved in the sensing of plasma glucose concentration." (PMID 33919776, 2021). "Three studies demonstrated the similarity of this glucagon molecule and of traditional glucagon kits in insulin-induced hypoglycemia in adults and children." (PMID 34638984, 2021). "In contrast, glucagon responses to insulin-induced hypoglycemia remain present, but diminished, in C-peptide–positive patients with T1D, with the magnitude of this response being proportional to the rise in C-peptide after a mixed-meal tolerance test." (PMID 34003799, 2021). "The long period from the original finding to pharmaceutical development and final approval of IN glucagon for hypoglycemia is probably one reason why several citations of the pioneering work are absent or confused in the scientific literature." (PMID 34638984, 2021). "The immediate correction of hypoglycemia by injection of recFABP4 further supports a necessary hormonal role for FABP4 in maintaining normoglycemia by correcting the impaired glucagon-mediated glycogenolysis as we previously suggested." (PMID 34676825, 2021). "Intake of 600 mg GABA more than doubled the glucagon, epinephrine, growth hormone and cortisol responses to hypoglycemia." (PMID 34635547, 2021). "Given the relatively small increase in circulating copeptin in response to hypoglycemia, we used pharmacological and genetic approaches to more conclusively establish the link between AVP and counter-regulatory glucagon during hypoglycemia." (PMID 34787082, 2021).
Hypoglycemia (continued). "Dysregulation of glucagon secretion in type 1 diabetes (T1D) involves hypersecretion during postprandial states, but insufficient secretion during hypoglycemia." (PMID 33753784, 2021). "Hypoglycaemia at a plasma glucose concentration of 0.8–1.0 mM in the clamp induced 25-fold increase in epinephrine and sixfold and threefold increase in glucagon for healthy and diabetic pigs, respectively." (PMID 33727615, 2021). "We can foresee that because of ease of administration of the three new formulations the use of glucagon to resolve severe hypoglycemia will likely expand dramatically." (PMID 34638984, 2021). "Treatment of hypoglycemia is traditionally based on administration of carbohydrates or of glucagon via intramuscular (IM) or subcutaneous injection (SC)." (PMID 34638984, 2021). "When considered in the context of the current results, it is possible that the glucagon responses to insulin-induced hypoglycemia would be proportional to the quantity of residual C-peptide." (PMID 34003799, 2021). "Consistent with hypoglycemia, fasting plasma glucagon levels were significantly increased in Polg mice compared to WT mice." (PMID 34652935, 2021). "The main indication for glucagon is hypoglycemia in insulin-treated diabetic patients; however, congenital hyperinsulinism and alimentary hypoglycemia in infants are also amenable to glucagon." (PMID 34638984, 2021). "α cells secrete glucagon in response to hypoglycemia and β cells secrete insulin in response to hyperglycemia." (PMID 35002748, 2021). "GLP-1 RAs increase insulin secretion and inhibit the glucagon action in a glucose-dependent manner, making it less likely for hypoglycemia." (PMID 34209532, 2021). "Only whole pancreas transplantation seems capable of restoring glucagon responses to hypoglycemia, while islet transplantation have shown discordant results with potential partial restoration of glucagon responses to hypoglycemia." (PMID 34405569, 2021). "In both T1D and T2D, the ability of glucagon to counteract insulin-induced hypoglycemia has been shown to be impaired." (PMID 34752420, 2021). "During GABA treatment (600 mg) a counter-regulatory response of glucagon, epinephrine, GH, as well as cortisol occurred in response to hypoglycemia." (PMID 34635547, 2021). "Calcium concentration correlates with glucagon exocytosis during hypoglycemia but uncouples during supraphysiological glucose levels." (PMID 33919776, 2021). "In hyperglycemia, insulin secretion is increased, and glucagon secretion is suppressed, whereas, in hypoglycemia, insulin secretion is inhibited, and glucagon secretion is increased, causing an increase in hepatic glucose production." (PMID 34199839, 2021). "Parasympathetic activity is increased during hypoglycemia to stimulate glucagon secretion and subsequent restoration of euglycemia." (PMID 34354571, 2021). "During hypoglycemia, glucagon secretion in CPEP was 2 times higher than SAL, and this increased net hepatic glucose output and reduced the amount of exogenous glucose required to maintain glycemia." (PMID 34003799, 2021). "2DG is a non-metabolizable glucose molecule that evokes a state of perceived glucose deficit (mimicking hypoglycemia) and triggers a robust counter-regulatory stimulation of glucagon secretion." (PMID 34787082, 2021). "It is possible, at the end of the test, to perform a glucagon 1 mg infusion and if glucose increases to >25 mg/dL, this confirms the diagnosis of hypoglycemia secondary to endogen insulin secretion, as high insulin levels block glycogenolysis." (PMID 34199977, 2021). "Plasma glucose, glucagon, C-peptide, insulin, epinephrine and platelet aggregation responses were measured before, during and after hypoglycaemia." (PMID 33727615, 2021).
Hypoglycemia (continued). "The phenotype study was particularly focused on glucose and insulin homeostasis: these mice displayed hypoglycemia in the fasted state secondary to impaired fasting-induced glucagon increased and impaired gluconeogenesis induction in the liver." (PMID 34201257, 2021). "Even though it has been available for long time and approved by ADA for resolution of hypoglycemia, injected glucagon has been under-utilized in the US, in Europe, and in Japan." (PMID 34638984, 2021). "Numerous clinical studies have shown that T1D patients who have an “insulinogenic reserve,” also referred to as being “C-peptide positive,” experience diminished glucose variability and enhanced plasma glucagon responses to insulin-induced hypoglycemia." (PMID 34003799, 2021). "Novel available glucagon formulations, even now, allow clinicians to deal with hypoglycemia differently with respect to past years." (PMID 34572493, 2021). "Plasma glucagon levels were significantly elevated in hypoglycemia male [M-V/INS versus M-V/V] and female [F-V/INS versus F-V/V] rats." (PMID 33490375, 2021). "During hypoglycemia, glucagon secretion also serves as feedback to protect the organism from the detrimental effects of low glucose levels in neurons and other cell types (glucopenia)." (PMID 34752420, 2021). "The increase in the blood pressure is considered as a result of elevated activity in the sympathetic nervous system due to hypoglycemia as a reaction to the hyperglycemic effect of glucagon." (PMID 34300215, 2021). "At the same time, adrenaline is believed to induce secretion of glucagon from roughly all α-cells, to rescue the body from hypoglycemia." (PMID 34460580, 2021). "If glucagon is used to solve an acute problem (hypoglycemic event or Severe Hypoglycemia), often in an emergency, is the administration route important?" (PMID 34572493, 2021). "In streptozotocin-induced diabetic rats, VMH AICAR injection can augment both glucagon and adrenaline responses during hypoglycemia." (PMID 34975743, 2021). "If SSTR-2, SSTR-3 and SSTR-5 are not expressed or have a low tumor expression, SSAs can lead to paradoxical hypoglycemia because they also inhibit counterregulatory hormone secretion (i.e., glucagon and growth hormone)." (PMID 34199977, 2021). "Hyperinsulinemic hypoglycemia was confirmed with glucagon test and whole-exome sequencing (WES) found a novel heterozygous splicing-site mutation (c.674-1G > A) in KMT2D gene." (PMID 32948218, 2020). "In hypoglycemia, increasing sympathetic nerve activity promotes liver glucose production, reduced insulin secretion, and increased glucagon secretion." (PMID 33817219, 2020). "After adjusting for hyperinsulinemia, early glucagon correlated with glycemic nadir (p<0.01), and prevented postprandial hypoglycemia (p<0.05)." (PMID 33424773, 2020). "At present, glucagon is mainly used as an emergency treatment to counteract severe, insulin-induced hypoglycaemia and is injected either SC or intramuscularly (IM)." (PMID 32792580, 2020). "In dogs, the bilateral resection of CB impaired the counterregulatory responses to hypoglycemia, reducing levels of cortisol and glucagon." (PMID 32698380, 2020). "During a provocative meal test, a positive correlation between early postprandial glucagon excursion and later glycemic nadir was identified, disclosing a potential role for glucagon in preventing hypoglycemia." (PMID 33424773, 2020). "We also assessed the glucagon level in the serum and found that Cavin1−/− mice had a higher level of glucagon than their wild‐type littermates due to their hypoglycemia." (PMID 33042738, 2020). "Hepatic vagal afferents reportedly act as a glucose sensor, as the mean rate of hepatic neural activity decreased following an injection of glucagon to induce hyperglycemia, but increased in response to insulin‐induced hypoglycemia." (PMID 32512650, 2020).